ARID3B (AT-rich interaction domain 3B)
Diseases named in the same sentence as ARID3B in open-access papers (continued):
Sharing a sentence is not in itself a finding about the gene and the disease.
germ cell tumor (1 paper, 2025). A benign or malignant, gonadal or extragonadal neoplasm that originates from germ cells. "ARID3B is frequently co-expressed with MYCN in germ cell tumors, ESCs, and testis—cell types associated with pluripotency." (PMID 39999848, 2025).
kidney tumors (1 paper, 2015). "ARID3B is increased in kidney tumors compared to normal kidney while ARID3A decreases." (PMID 26121572, 2015).
non-small cell lung carcinoma (1 paper, 2022). A group of at least three distinct histological types of lung cancer, including non-small cell squamous cell carcinoma, adenocarcinoma, and large cell carcinoma. "Then the relative gene and protein expressions of let-7f and its target genes, including HMGA2, ARID3B, SMARCAD1, and FZD3, were measured in lung tissues of Non-Small Cell Lung Cancer (NSCLC) patients and A549 cell line using quantitative real-time PCR and Western blotting." (PMID 35488374, 2022).
oral squamous cell carcinoma (1 paper, 2016). "A recent publication reported that suppressing Let-7 increased Oct4 and Sox2 expression in CSC-like oral squamous cell carcinoma (OSCC) by targeting ARID3B and HMGA2, which directly interact with Oct4 and Sox2." (PMID 26983719, 2016).
pancreatic cancer (1 paper, 2022). "In another study, miR-1291 delivery along with gemcitabine and nab-paclitaxel to pancreatic cancer reported induced DNA damage, mitotic block, induced apoptosis, and significant inhibition of tumor cells growth by upregulating the AT-rich interactive domain-containing protein 3B (ARID3B) gene." (PMID 35456698, 2022).
serous papillary adenocarcinomas (1 paper, 2012). "We also examined expression of ARID3B isoforms in a tissue blot from Imgenex that contained lysates from seven different serous papillary adenocarcinomas and their matching normal adjacent tissue." (PMID 22860069, 2012).
stomach tumors (1 paper, 2015). "Conversely, ARID3A is increased in stomach tumors compared to normal stomach; ARID3B decreases during stomach tumor progression." (PMID 26121572, 2015).
virus infection (1 paper, 2016). "Using RT-qPCR analysis of the KSHV ORF57 gene as a measure of virus infection, we demonstrated that knockdown of ARID3B led to an enhancement of virus infection, suggesting that ARID3B knockdown led to an increase of released virions." (PMID 27512077, 2016).
tumor (18 papers, 2012 to 2026). "ARID3B (AT-Rich Interaction Domain 3B) encodes for a DNA binding protein and has been described as contributor to tumor initiation and progression in cancerous diseases." (PMID 33142733, 2020). "We next depleted ARID3B in CRC PDXs by intratumoral injection of the integrase-deficient lentiviral vector (IDLV)-CRISPR/Cas9 system 40 into PDXs on the 7th day after tumor inoculation." (PMID 32483441, 2020). "Since ARID3B is expressed in stem cells and associates with stem cell factors, we hypothesized that ARID3B promotes tumor growth through the regulation of a CSC phenotype." (PMID 25327563, 2014). "ARID3B, a DNA-binding protein overexpressed across multiple tumor types, expands the cancer stem cell population by regulating these pathways." (PMID 41972703, 2026). "Here, using an in vivo CRISPR/Cas9 screen in a CMT93 cell-derived murine tumor model, we identify Arid3b as a key negative regulator of CD8+ T cell infiltration and antitumor activity." (PMID 42140952, 2026). "Further proliferation, migration, and invasion assays also confirmed that silencing ARID3B effectively reversed the promotion of tumor cell proliferation and metastatic potential by RGS3 overexpression." (PMID 40456746, 2025). "ARID3B, a member of the AT-rich interactive Domain protein family, plays crucial roles in embryonic development and tumor growth." (PMID 40456746, 2025). "The analysis of xenograft tumor growth showed that suppression of ARID3B significantly inhibited tumor growth." (PMID 32483441, 2020). "A xenotransplantation assay showed that the ectopic expression of ARID3B promoted tumor growth in HT-29 cells more prominently when inoculating a lower cell dose." (PMID 32483441, 2020). "Our data demonstrate that ARID3B regulates a number of tumor promoting pathways and ARID3B overexpression leads to increased tumor growth and metastasis." (PMID 26121572, 2015). "Previous work identified the DNA binding protein ARID3B as a critical regulator of embryonic development and tumor growth." (PMID 26121572, 2015). "We chose to use these cells because ascites fluid contains CSCs, which contribute to aggressive tumor behavior and because ARID3B is found in stem cell populations." (PMID 25327563, 2014). "To assess how ARID3B contributes to the increased tumor growth in vivo, we identified ARID3B induced genes in tumor ascites cells." (PMID 25327563, 2014). "We next assessed if ARID3B enhances tumor development in vivo by altering cells intrinsic phenotypes." (PMID 25327563, 2014). "We therefore repeated this study to determine how ARID3B influenced tumor growth, survival, and gene expression." (PMID 25327563, 2014). "We propose that one mechanism for ARID3B enhancement of tumor growth is through activation of genes involved in CSC pathways leading to CSC production and paclitaxel resistance." (PMID 25327563, 2014). "Further work will address how localization and dosage of ARID3B regulates tumor cell growth and survival." (PMID 22860069, 2012). "Together, targeting ARID3B could offer a promising strategy to reshape the tumor microenvironment and sensitize MSS CRC to immunotherapy." (PMID 42140952, 2026). "In addition, previous research has shown that ARID3A and ARID3B jointly regulate gene expression in B-cells and cancers, regulate stem cell-related genes, and promote the phenotype of tumor stem cells." (PMID 36034939, 2022). "Gene set enrichment analysis (GSEA) was performed to investigate the association between the ARID3B-regulated signatures and CRC patient gene expression profiles from the public dataset (GSE17538), which contains the gene expression profile of tumor samples from 238 colorectal cancer patients." (PMID 32483441, 2020). "However, the role of ARID3B in tumor development is complicated, due to the large number of targets, and seemingly contradictory roles of ARID3B in cellular behavior." (PMID 26121572, 2015). "ARID3B increases tumor growth and activates cell death pathways." (PMID 26121572, 2015).
tumor (continued). "In particular, ARID3B induction of the Wnt receptor FZD5 is important in increasing tumor cell adhesion, which may contribute to metastasis." (PMID 26121572, 2015). "Overexpression of ARID3B increased tumor burden and decreased survival." (PMID 25327563, 2014). "Therefore, we performed a microarray to identify putative ARID3B regulated genes that are induced by ARID3B in our tumor model." (PMID 25327563, 2014). "The results indicate that ARID3B alters cell-matrix adhesion, which may contribute to increased tumor growth in vivo." (PMID 25327563, 2014). "ARID3B Sh was also expressed in tumor tissue and in some normal adjacent lysates." (PMID 22860069, 2012). "Therefore ARID3B induces stem cell genes, which may contribute to the increased tumor production in xenografts expressing ARID3BFL." (PMID 25327563, 2014). "Genetic ablation of Arid3b in CD8+ T cells significantly enhances their intratumoral accumulation and promotes robust tumor control." (PMID 42140952, 2026). "This miRNA targets oncogenes and important genes for the initiation and progression of the tumor, including Myc, RAS, E2F1, E2F5, LIN28, ARID3B, PBX3, HMGA2 and long non-coding RNA H19." (PMID 36833380, 2023). "Let-7 serves as a potent tumor suppressor through post-transcriptional repression of a number of oncogenic mRNA targets including DICR1, ARID3B, HMGA2 and MYCN." (PMID 36505784, 2022). "A nonsignificant difference was found in the expression level of ARID3B and SMARCAD1 between the tumor and control tissues (p > 0.05)." (PMID 35488374, 2022). "ARID3B, CXCR1, GATS, Itga6, Shh, SLC27A5, STC2, and VEGF play an important role in cell proliferation and tumor progression or metastasis." (PMID 35875133, 2022). "The results showed that all three samples expressed a high level of ARID3B, which indicates the importance of ARID3B in tumor initiation and propagation and justifies the application of CRISPR/Cas 9 to deplete ARID3B in these tumors for subsequent experiments." (PMID 32483441, 2020). "Research has shown that ARID3B induces Wnt receptor FZD5, which is important for enhancing tumor cell adhesion and may contribute to metastasis." (PMID 40456746, 2025). "Additionally, immunohistochemistry revealed protein-level accumulation of two candidate genes, ARID3B and GINM1, in both precursor and tumor cells." (PMID 39999848, 2025). "Additionally, through immunohistochemistry, we demonstrated the protein-level accumulation of two candidate genes, ARID3B and GINM1, in both precursor and tumor cells." (PMID 39999848, 2025). "The mRNA expression of ARID3A, ARID3B, ARID4B, JARID1B, JARID1C, JARID2 in tumor tissues was more expressive in normal tissues, ARID1B, ARID3C, ARID4A, ARID5A, ARID5B, JARID1A mRNA expression in tumor tissues were lower than that in the normal tissues (p<0.05)." (PMID 33592583, 2021). "ARID3B is a DNA binding protein, however how ARID3B regulates tumor pathways has not been investigated." (PMID 25327563, 2014). "We found that ARID3B increases tumor growth in vivo and induces CSC genes in tumor ascites." (PMID 25327563, 2014). "We found that ARID3B Fl was expressed in tumor tissue but not normal adjacent tissue." (PMID 22860069, 2012).
cancer (11 papers, 2012 to 2026). A tumor composed of atypical neoplastic, often pleomorphic cells that invade other tissues. "ARID3B induced expression of genes associated with metastasis and cancer stem cells (CD44, LGR5, PROM1 (CD133), and Notch2)." (PMID 25327563, 2014). "Therefore, many of the target genes that are ARID3B-regulated are implicated in cancer." (PMID 26121572, 2015). "Because the stemness signatures and their regulatory mechanisms are distinct among different cancers 43, 44, we investigated the role of ARID3B in the tumorigenesis and stemness of CRC." (PMID 32483441, 2020). "ARID3A inhibits cell differentiation, promotes cell proliferation, and increases survival potential of cells, whereas ARID3B promotes proliferation, invasion, and migration of cancer cells." (PMID 32455665, 2020). "The specific gene targets we discovered provide insight into how ARID3B acts during development and in cancer." (PMID 26121572, 2015). "In conclusion, our study demonstrated, for the first time, the presence of an alternate splice form of ARID3B and confirmed that both splice forms of ARID3B are present in a variety of cancer cell lines." (PMID 22860069, 2012). "The expression of both splice forms, ARID3B Fl and ARID3B Sh, was observed in all nine cancer cell lines." (PMID 22860069, 2012). "This splicing yields a 28 kDa isoform, ARID3B Sh, which is highly expressed in several cancer cell lines." (PMID 22860069, 2012). "Collectively, these findings reveal phosphorylation as a previously unrecognized molecular switch that dictates ARID3B's localization and transcriptional activity, providing novel insights into cancer stem cell regulation and identifying a potential targetable vulnerability in aggressive tumors." (PMID 41972703, 2026). "We therefore hypothesized that ARID3B-regulated target genes are cell-type specific, and the understanding of the molecular context will extend our knowledge of how ARID3B regulates cancer stemness." (PMID 32483441, 2020). "The differential mechanisms of ARID3B may explain the context dependency of CSC factors among different cancers." (PMID 32483441, 2020). "Moreover, ARID3B increased the number of CD133+ (a cancer stem cell marker) cells compared to control cells." (PMID 25327563, 2014). "Additionally, many pathways involved in both development and cancer are regulated by ARID3B." (PMID 26121572, 2015). "This suggests that ARID3B’s role in cancer may be context dependent." (PMID 26121572, 2015). "Other oncogenes such as MYCN may more strongly induce ARID3B in human cancer." (PMID 22860069, 2012). "In cancer cells, ARID3A and ARID3B recruit histone demethylase 4C (KDM4C) to make a tri-protein complex, called the ARID3B complex." (PMID 32455665, 2020). "To address the role of ARID3B in ovarian tumorigenesis, we performed mouse xenograft assays using SKOV3IP cells expressing exogenous ARID3BFL at levels similar to what is observed with IHC in human cancer." (PMID 25327563, 2014). "However the function and regulation of ARID3B in cancer has not been fully evaluated." (PMID 22860069, 2012).
infection (1 paper, 2016). The state of being infected such as from the introduction of a foreign agent such as serum, vaccine, antigenic substance or organism. "To ask if the increases in lytic cycle-associated expression and genome replication led to an enhanced productive infection, we harvested and clarified medium from iSLK-BAC16 cells that had been transfected with ARID3B siRNA and reactivated with doxycycline." (PMID 27512077, 2016).
ARID3B also shares sentences with these, for which no sentence is quoted: benign ovarian tumors (1 paper); Blepharocheilodontic syndrome 2 (1); Branchio-oculo-facial syndrome (1); Cirrhosis (1); embryonal carcinoma (1); glioblastoma (1); gynecologic tumors (1); hepatocellular adenoma (1); liver cancer (1); lung carcinoma (1); Obesity (1); s Sarcoma (1); seminoma (1); stomach cancer (1).